ATM (ATM serine/threonine kinase)
Diseases named in the same sentence as ATM in open-access papers (continued):
Sharing a sentence is not in itself a finding about the gene and the disease.
infection (continued). "These stresses including reactive oxygen species (ROS), DNA alkylation, topoisomerase poisons, repair deficiency, telomere shortening, meiosis breaks, and infection can activate ataxia telangiectasia, rad3-related (ATR), DNA-dependent protein kinase (DNA-PK) and ataxia telangiectasia mutated (ATM)." (PMID 25105411, 2014). "Taken together, these results strongly suggest that even in a permissive system, HO gets inactivated by 4 h time point after infection, limiting its cleavage activity to just once in an experimental window of 0-12 h, or at least all the period in which ATM remains active." (PMID 24655462, 2014). "Likewise, in the case of Listeria, we show that downregulation of Mre11 or ATM or H2AX favors infection." (PMID 25340842, 2014). "For example, simian virus type 40 (SV40), herpes simplex virus 1(HSV-1), HCMV, and Epstein-Barr virus (EBV) all activate ATM and downstream signaling during infection, which is accompanied by recruitment of ATM and other repair proteins to sites of viral DNA replication." (PMID 24859341, 2014). "Similarly to the results obtained in Mre11ATLD MEFs, we observed at 24 hours of infection a higher GFP signal in ATM deleted fibroblasts compared to the wild-type cells." (PMID 25340842, 2014). "The prevention of ATR signaling during infection may predispose viral replication forks to collapse which in turn may lead to DSB formation, ATM activation and homology directed repair." (PMID 24098119, 2013). "Similarly, in the late phase of infection, inhibition reduced viral DNA monomers to a level comparable to that observed when ATM was inhibited during the early phase, yet total viral DNA was only insignificantly decreased compared to DMSO-treated cells." (PMID 23592994, 2013). "Yet surprisingly, when undigested total intracellular DNA from an ATM-inhibited infection was analyzed by 2 d gel electrophoresis, bidirectional replication was still observed (data not shown) and unit length viral DNA remained the predominant product when ATM was inhibited." (PMID 23592994, 2013). "Thus, inhibition of ATM throughout infection reduced monomeric and increased concatemeric SV40 DNA products." (PMID 23592994, 2013). "The top differentially regulated host pathways associated only with wild-type strain infection are involved with immunomodulation and cell cycle arrest, such as PPAR/RXR activation pathway, G2/M DNA damage checkpoint, ATM signaling and the PDGF signaling pathway." (PMID 23516652, 2013). "Interestingly, inhibition of ATM and its downstream kinase Chk2 early in infection markedly increases the efficiency of transformation suggesting that the DDR blocks early events in EBV-mediated B-cell outgrowth." (PMID 22240795, 2012). "Therefore, host chromosomal changes mediated by disruption of RB/E2F1 complexes or other mechanisms of E2F1 deregulation should also be considered as possible ATM activators during infection." (PMID 21589897, 2011). "Recent data have shown that several viruses, including herpes simplex virus type 1 (HSV-1), polyomavirus, human papillomavirus (HPV), and human immunodeficiency virus type 1 (HIV-1) require the activation of ATM and/or downstream proteins for a fully permissive infection." (PMID 21589897, 2011). "Moreover, we show that ATM and downstream signaling are required for replication following infection at a low MOI and contributes to HCMV replication at higher doses." (PMID 21589897, 2011). "Indeed the frequency of syncytia exhibiting the phosphorylation of ATM and that of the ATM substrate γ-H2AX was similar after infection with HIV-1 WT and HIV-1 IND64V." (PMID 18560558, 2008).
infection (continued). "In addition, CV-B5/F infection increased p-DNA-PK, p-ATM, and p-H2AX levels in NCI-H460 cells." (PMID 37743418, 2023). "Interestingly, we report Mre11-dependent restriction of replication, indicating that Mre11 and ATM may play independent, and possibly opposing, roles during infection." (PMID 33563816, 2021). "Notably, occurrence of nuclear DNA damage and damage-induced nuclear foci were observed at later hours of infection (12 hpi) when maximal activation response of ATM-Chk2 pathway has subsided, indicating a temporal distinction between the canonical DDR and the virally manipulated skewed response." (PMID 33818275, 2021). "Thus, we hypothesized that ATM activation upon infection may be channeling survival signals through alternate pathways." (PMID 32223892, 2020). "Taking advantage of this, we examined the phosphorylation status of SQ/TQ motif-containing proteins in HeLa cells to investigate whether the ATR/ATM arms of the DNA damage response are activated by infection with the Western Reserve (WR) strain of vaccinia virus." (PMID 28467896, 2017). "Next, we determined whether ATM is responsible for γH2AX accumulation following infection." (PMID 21589897, 2011). "As an additional control, we monitored another ATM substrate that also binds UL12, Nbs1, that is known to be phosphorylated after infection (20, –, 22)." (PMID 40824090, 2025). "A temporal analysis of our data revealed that, during the early stages of infection, there was an increase in XPA and ATM expression, indicating the activation of the nucleotide excision repair (NER) and homologous recombination (HR) pathways, respectively." (PMID 40429613, 2025). "DNA viruses, such as human bocavirus 1 (HBoV1) infection, induce a DDR with activation of ATM, ATR, and DNA-PKcs." (PMID 40008889, 2025). "Inhibition of the top hit, ATM, has already been shown to restore exhausted CD8+ T-cell function in an HCV-infection context." (PMID 39689157, 2024). "Strikingly, AdV has a much more complex serotype-specific interaction with MRN and ATM, suggesting that viruses have evolved different strategies to overcome the host DDR during infection." (PMID 38932138, 2024). "Our study demonstrated high potency of ATM-AVI (MIC90 0.25–1 μg/mL) against MDR Enterobacterales, with ≥98.5% and ≥99.1% isolates, from wards and infection sources, respectively, inhibited at the tentative breakpoint of ≤8 μg/mL globally and in all regions." (PMID 37998793, 2023). "Our study also identified potent activity of ATM-AVI (MIC90 0.25–1 μg/mL) against ESBL-positive isolates across wards and infection sources, with ≥98.6% and ≥99.1% isolates, respectively, inhibited at ≤8 μg/mL globally and in all regions." (PMID 37998793, 2023). "ATM deregulation both depends and triggers IFN signaling following DDR perturbations and infections." (PMID 36306362, 2022). "ATM activity has been shown to promote HSV-1 gene expression and replication in some infection conditions but is dispensable in others (36, –, 38)." (PMID 33563816, 2021). "The Ad5 E4orf4 protein was also shown to inhibit the ATM and ATR signaling pathways that were activated during infection with an E4-mutant Ad, and it required its major partner, PP2A, for this function." (PMID 32906746, 2020). "We observed that 24 h post infection, MRE11 was found downregulated, whereas RAD50, CTIP, and ATM were found upregulated in a CagA-independent manner." (PMID 33339161, 2020). "Western blot analyses showed that both ATM and ATR were phosphorylated following infection with pks+E. coli or after MMC treatment." (PMID 29559578, 2018).
infection (continued). "The closely related BKV has also been reported to induce the DDR: infection of the natural host cells of the virus, renal proximal tubule epithelial (RPTE) cells, activated both the ATM and the ATR (ATM and Rad3-related) DDR." (PMID 28202068, 2017). "We conclude that both ATM and DNA-PKcs are activated in BMDMs by LPS and IFN-γ or infection with L. monocytogenes, and that these kinases can have unique (ATM phosphorylation of KAP-1) or overlapping (ATM or DNA-PKcs phosphorylation of H2AX) functions." (PMID 28362262, 2017). "Vaccinia-induced phosphorylation of Chk1 and Chk2 further established that infection activates the ATR and ATM pathways." (PMID 28467896, 2017). "Using specific ATM and ATR inhibitors to target viral replication, particularly genome amplification in differentiated cells, as the loss of FA-dependent episomal maintenance could lead to increased rates of integration, may reduce the cells ability to support successful infection." (PMID 28820495, 2017). "Thus at 42 hrs post infection, dl366* produced 11-fold more progeny virus in A-T cells than in WT cells (ln(fold change = 2.46) and dl366*+E4orf4 produced 17-fold more progeny virus (ln(fold change = 3), indicating that ATM inhibits virus replication as was recently reported." (PMID 26867009, 2016). "During infection by HSV-2, H2AX phosphorylation was similarly dispensable but was dependent on both ATM activity and viral DNA replication." (PMID 26817608, 2016). "Inhibition of the DDR regulators ATM and ATR, as well as expression of E4orf4, enhances infection efficiency." (PMID 26867009, 2016). "Activation of ATM, phosphorylation of H2AX, and the recruitment of DNA repair factors to viral replication centers are observed upon infection with multiple DNA viruses, including SV40, HCMV, HSV-1, KSHV, EBV, MCPyV, and γHV68." (PMID 27310012, 2016). "Although the study of early events in KSHV de novo infection of primary cells has been limited, KSHV infection of immortalised endothelial cells in vitro induces the ATM signalling pathway." (PMID 22240795, 2012). "We assessed the involvement of ATM and ATR during infection using small interfering RNA (siRNA) knockdowns." (PMID 22952448, 2012). "Following infection, key components of the DDR, like ATM, RPA, ATRIP, 53BP1, γ-H2AX are recruited into viral replication centers, with PML NBs juxtaposed to these." (PMID 21998700, 2011). "The ATM-dependent DDR is detected as discrete, nuclear γH2AX foci early in infection and can be activated by IE proteins." (PMID 21589897, 2011). "Both caffeine and LY294002 reduced the caspase 3 activation observed upon infection, which further supported the notion that the induction of apoptosis by CDT was ATM-dependent." (PMID 20668524, 2010). "Since MRN is required for robust ATM signaling, it is possible that it plays important roles early in MVM infection to activate signaling but must be degraded at late times due to an inhibitory function." (PMID 20949077, 2010). "In normal primary fibroblasts, the presence of viral DNA in NBS1, ATM, and ATR immunoprecipitates was first detected 12 hrs post-infection." (PMID 18211700, 2008). "In infected cells, ATM is activated early during infection, and the activation does not occur in the absence of DNA replication." (PMID 40824090, 2025). "Under the same conditions, depletion of ATM in MOLT-3 showed no significant impact on viral replication 96 h post-infection." (PMID 38177923, 2024). "(2020) we here confirmed for a primary host cell type that ATM-mediated repair signaling is induced in T. gondii RH-infected BUVEC whilst the ATR-dependent pathway was not affected by infection." (PMID 38524184, 2024). "This is in agreement with a study from the SENTRY database between 2019 and 2020 on Enterobacterales isolates collected from Europe, which showed that ≥99.6% isolates were inhibited by ATM-AVI irrespective of infection sources." (PMID 37998793, 2023).
infection (continued). "However, γ-H2AX levels are negatively correlated with ATM and DNA-PK activation after EVA71 infection." (PMID 35067196, 2022). "Indeed, several ATM-DDR signalling components, including ATM, γH2AX, Chk2 and BRCA1, are localized to the sites of viral replication during an infection, perhaps to ensure high-fidelity genome replication." (PMID 33427604, 2021). "While both ATM and the related ATR DDR kinase appear to be activated by infection, it is unclear whether they affect replication." (PMID 33563816, 2021). "Mre11 depletion did not totally abolish ATM activation, indicating a redundant mechanism for ATM activation in response to infection." (PMID 33563816, 2021). "Having observed the requirement of ATM for a robust DDR, we hypothesized that the MRN complex may have facilitated this phenotype by activating ATM in response to infection." (PMID 33563816, 2021). "At the early stages of infection, the MRN DSB sensor binds viral genomes and activates a local ATM-dependent anti-viral response that would inhibit viral replication in the absence of MRN-inactivating Ad proteins without interfering with cellular DNA replication." (PMID 32906746, 2020). "To interrogate the role of phosphorylated H2AX in infection of human fibroblasts by HSV-1 and HSV-2, we inhibited ATM and ATR activity using three approaches: chemical inhibitors of ATM or ATR kinase activity, siRNAs specific for ATM and ATR, and cell lines deficient in either ATR or ATM." (PMID 26817608, 2016). "To validate the hit, we first repeated the infection of AALE cells with the individual ATM shRNA in the absence of HRAS." (PMID 27922010, 2016). "As expected, infection of PCV2 alone activated caspase-3 in the cultured cells, whereas their activities were significantly decreased in the infected cells when treated with the ATM, ATM/ATR, or DNA-PK inhibitor." (PMID 27982097, 2016). "This technique also revealed higher levels of infection in 53BP1, H2AX and ATM knocked down cells." (PMID 25340842, 2014). "Taken together, the results demonstrate that ATM activity was beneficial but not essential during the early phase of infection, whereas it was vital for the assembly and/or stability of viral replication centers during the late phase of infection." (PMID 23592994, 2013). "Taking the results together, we infer that SV40-infected cells require ATM signaling, primarily during the late phase of infection, to favor production of unit-length genomes rather than aberrant products." (PMID 23592994, 2013). "Inhibition of ATM reduced the level of 5.2 kbp viral DNA products migrating as form I (supercoiled), form II (nicked), and form III (linear), relative to that in the DMSO-treated control infections (compare lanes 1–4 to 5–8)." (PMID 23592994, 2013). "A short lived ‘booster effect of infection’ was observed in the GERBUTM and Quil ATM groups while the highest level of in-vitro inhibition of C2 activity was observed for the IgGs from the Quil ATM group." (PMID 22621378, 2012). "However, even though H2AX can be phosphorylated by other kinases later during infection, activated ATM is mostly located in HCMV RCs at these times pi, leaving open the possibility that ATM is influencing activities in these nuclear compartments." (PMID 21589897, 2011). "It will be interesting to determine whether ATM is only transiently responsible for host DDR signaling (and viral replication) during infections with herpesviruses." (PMID 21589897, 2011). "Finally, we observed that USP15 is phosphorylated early during infection, and the phosphorylation is independent of ATM or DNA synthesis." (PMID 40824090, 2025). "Although ATM is important for virus replication in cells, HCMV replication in cells lacking ATM has also been reported, Some DDR proteins have been shown to mislocate from the nucleus to the cytoplasm after infection, blocking checkpoint signaling and inhibiting host DDR." (PMID 37915066, 2023).
infection (continued). "Interestingly, inhibition of ATM and Chk2 by targeted small molecules (ATM inhibitor KU55933, Chk2 inhibitor BML-277) significantly abrogated fusion and maturation of viroplasms with progression of infection leading to heavily restricted rotaviral propagation." (PMID 33818275, 2021). "Subsequent studies found that along with ATM, many of the pathway’s upstream and downstream components are also required for viral replication, suggesting that the ATM pathway may be activated canonically by HPV during infection." (PMID 28820495, 2017). "Therefore, ER stress signaling, but not ATM activity, regulates the increase in ROS during infection." (PMID 26938301, 2016). "However, a reduction in phosphorylation of all tested Chk1 phospho sites was observed upon infection with dl366*+E4orf4, suggesting that ATM was not required for the reduced phosphorylation of ATR substrates induced by E4orf4." (PMID 26867009, 2016). "Following infection of human foreskin fibroblasts by HSV-1 or HSV-2, we assayed the phosphorylation of H2AX in the presence of inhibitors of transcription, translation, or viral DNA replication, or in the presence of inhibitors of ATM and ATR kinases (KU-55933 and VE-821, respectively)." (PMID 26817608, 2016). "Our study identifies important links between innate immune signaling, the ATM DNA damage pathway and productive HPV replication that may lead to the characterization of new targets for the development of therapeutics to treat HPV-induced infections." (PMID 23593005, 2013). "HCMV gene expression patterns in infected cells lacking or depleted for ATM may offer clues to the stage(s) in infection that depend on ATM function." (PMID 21589897, 2011). "Importantly, infection with HIV-1 IND64V (but not HIV-1 EnvVSV) was as efficient in eliciting ATM phosphorylation as HIV-1LAI, both in CD4+CXCR4+ HeLa cells and in CEM cells (not shown)." (PMID 18560558, 2008). "Similar in vitro ATM-AVI activity was also observed irrespective of region, in which ≥99.7% Enterobacterales isolates from these infection sources were inhibited by ATM-AVI at ≤8 μg/mL (MIC90 of 0.12–0.25 μg/mL) in AfME, APAC, Europe, LATAM, and North America." (PMID 37998793, 2023). "Bocaparvovirus minute virus of canines (MVC) infection results in activation of both ATM and ATR cascades but not DNA-PKcs, and only ATM activation is required for efficient viral replication and progeny production." (PMID 34878919, 2022). "In particular, in a recent study examining DDR activation in EBV-exposed B cells, ATR/Chk1, but not ATM/Chk2 pathway, was activated, while specific targeting of ATR was able to suppress B cell aberrant function upon the infection." (PMID 36306362, 2022). "Treatment of A549 cells with non-toxic concentrations of the inhibitors for ATM and Chk2 prior to stimulation with H2O2, etoposide or infection with SC35M clearly demonstrated that these kinases are not involved in IAV-mediated TRIM28 S473 phosphorylation." (PMID 30323812, 2018). "Efficient replication of the HSV-1 genome is limited in the absence of host factors such as ATM, MRN, or WRN, indicating that such factors promote productive infection." (PMID 29144403, 2017). "It has been suggested that, in the context of infection with Ad5 mutant viruses lacking E4 and unable to interfere with the MRN complex, ATM plays an important role in viral inhibition." (PMID 28791251, 2017). "Notably, while our data rule out canonical DDR factors (ATM, ATR, DNA-PK), they do not address the interplay between DNA damage during infection and Vpr-induced TGF-β production." (PMID 40632811, 2025). "Infection of H-Lats with VprWT virus induced significantly higher eGFP expression compared to control infections, regardless of MOI, which could be ablated by caffeine or ATM/ATR-specific inhibitors." (PMID 39975144, 2025). "Levels of ATM and ATR were unchanged regardless of infection." (PMID 41186411, 2025).